CGA (glycoprotein hormones, alpha polypeptide)
Diseases named in the same sentence as CGA in open-access papers (continued):
Sharing a sentence is not in itself a finding about the gene and the disease.
tumor (351 papers, 1996 to 2025). "From a prognostic perspective, although elevated or rising CgA levels have been associated with increased tumor burden, liver metastases, and worse overall survival, findings are not entirely consistent." (PMID 40869136, 2025). "An increase of CgA > 40% from baseline in serial follow‐up was associated with a high risk of tumor progression or recurrence." (PMID 41427266, 2025). "Chromogranin A (CgA) in serum is a commonly used biomarker for assessing tumor burden and monitoring treatment response, with elevated levels associated with tumor malignancy." (PMID 40535122, 2025). "Positive ctDNA was associated with higher histopathological grades, primary tumour location (mostly pancreas), higher CgA, worse OS and worse progression-free survival (PFS)." (PMID 39409968, 2024). "The CgA level was associated with the tumor burden (i.e., the sum of the length of the lesions) and increased by 13% per cm (95% CI, 11%–15% per cm, P < 0.001)." (PMID 39453770, 2024). "In patients with unresectable disease or residual tumor after resection (group 3), age, proliferation, and p-CgA were identified as independent risk factors consistent with results from previous studies." (PMID 38201527, 2023). "CgA levels have been linked to tumor burden in Pan-NENs, whereas its prognostic role is more conflicting." (PMID 38137624, 2023). "Chromogranin A had been used as a valuable tumor marker in NETs and elevated levels of CgA and 5-HIAA as well, has previously been associated with poor prognosis was associated with poor outcome." (PMID 38317712, 2023). "Changes in CgA levels during PRRT should be interpreted with caution though, as an increase in CgA can be caused by both tumor progression and cell damage or lysis by PRRT." (PMID 36497273, 2022). "The presence of CTCs was linked to increased tumor burden, higher tumor grade, and elevated seric CgA." (PMID 35163032, 2022). "The diagnostic sensitivity and specificity of a decreased CgA level for tumor regression were 79% and 69%, respectively." (PMID 34868938, 2021). "A recently published prospective study showed only a weak association between changes of CgA and changes in tumour burden." (PMID 33244704, 2021). "They reported that increasing age at diagnosis, higher Ki-67, increasing urinary hydroxyindole acetic acid levels, higher CgA levels, high tumor volume, and resection of primary tumor were associated with a worse OS in the univariate analysis." (PMID 34868938, 2021). "The diagnostic sensitivity and specificity of an increased CgA level for tumor progression were 36% and 82%, respectively." (PMID 34868938, 2021). "CgA serum values, in contrast, exhibited a positive association with tumor stage and size (tumor stage: τ = 0.351, p < 0.001; tumor size: τ = 0.280, p = 0.005)." (PMID 30867449, 2019). "NETest results and chromogranin A (CgA) levels were compared with clinical information including radiological imaging to evaluate the association with tumor characteristics." (PMID 30564197, 2018). "The most studied tumor marker for pNETs is CgA; however, it has the disadvantage of frequently causing false positives due to the presence of multiple secretory processes that cause increases in its concentration." (PMID 29290942, 2017). "Structure-function studies showed that the C-terminal region of CgA contains a bioactive site and that cleavage of this region causes a marked loss of anti-angiogenic and anti-tumor potency." (PMID 27683038, 2016). "α-Fetoprotein levels associated strongly and positively with tumour grade, serum CgA and hCGβ levels, and worse survival." (PMID 18577995, 2008). "Elevated CgA levels were significantly associated with two independent parameters, namely the presence of other secretions (P = 0.0001) and a heavy tumour burden (P = 0.001)." (PMID 9792158, 1998).
tumor (continued). "At the same time, CgA can also promote the polarization of tumor-associated macrophages to M2 type." (PMID 39975592, 2025). "The lowest levels of CgA in both tumor regions might suggest a loss of activity and/or a down-expression of this protein in CRC, in accordance with a previous study." (PMID 39195201, 2024). "The serum CgA level may be associated with tumor burden, with smaller (<2 cm) ANENs often having normal CgA levels." (PMID 39456535, 2024). "They concluded a weak association between change of CgA and change in tumor burden." (PMID 34868938, 2021). "This hypothesis is further supported by the results of in vivo studies showing that inhibition of CgA cleavage in Panc02-bearing mice, by systemic administration of aprotinin, is associated with a lower tumor-growth rate." (PMID 33425767, 2020). "This may be due to improved diagnosis and the development of suitable, sensitive ways to measure this tumor, such as immunohistochemistry like chromogranin A (CgA) and diagnostic methods for tumor detection." (PMID 32563832, 2020). "Secondly, given that CgA is an ubiquitous protein and the growth factors such as IGFs are secreted by endothelial and other cells, the tumor in vivo microenvironment may have been able to compensate for the CgA-related loss." (PMID 30833285, 2019). "In patients with either localized or advanced (stage D2) PCa, strong CgA staining of primary tumor correlates with poorer cause-specific survival and overall survival and provides superior information as compared to currently used pathologic prognostic factors." (PMID 25785244, 2015). "Furthermore, the CgA concentration was associated with tumor burden (sum of the length of lesions)." (PMID 39453770, 2024). "However, the current single secreted biomarkers for pancreatic NETs, such as gastrin, insulin and chromogranin A (CgA), have limited usefulness for diagnostic or prognostic purposes, owing to the complexity and diversity of multiple tumour development and varying responses to different therapies." (PMID 35900839, 2022). "Although CgA expression reflects the secretory activity and granule content of tumor cells, making it a commonly used biomarker for diagnosis, prognosis, and treatment monitoring, its sensitivity for detecting early-stage or localized pNETs is suboptimal." (PMID 40869136, 2025). "For example, CgA can inhibit the proliferation and cytotoxicity of T lymphocytes and reduce their killing effect on tumor cells." (PMID 39975592, 2025). "In contrast, the tumor tissue was positive for CgA, Syn, and S - 100, confirming the diagnosis of HPGL." (PMID 40978045, 2025). "Compared with traditional biomarkers such as chromogranin A (CgA), ctDNA offers the distinct advantage of directly reflecting the tumor’s molecular landscape, potentially allowing earlier detection of disease progression." (PMID 40869136, 2025). "The immunophenotype of the tumor was as follows: CgA (+), Syn (+), CKAE1+E3 (+) “dot-like”, S100 (-), calcitonin (-), EMA (+/-), Ki67 3% to 4% in hot spots, no necrosis, mitotic index 0/10HPF with conclusion: thymic NET—typical carcinoid (low-grade)." (PMID 40071083, 2025). "Even after the same treatment, the regulatory mechanisms of CgA synthesis and release in tumor cells from different patients are different." (PMID 39975592, 2025). "If the proportion of neuroendocrine cells in the tumor is low, then the change of CgA level has limited effect on the overall tumor progression, and it is difficult to significantly correlate with the survival outcome." (PMID 39975592, 2025). "Diagnosis is confirmed by microscopic observation of the morphological features of the tumor cells and detection of the expression of neuroendocrine markers, such as synaptophysin (Syn), chromogranin (CgA), and CD56." (PMID 40248205, 2025).
tumor (continued). "We found that, with the exception of dNLR, all tested inflammatory parameters improved the prognostic ability of a base model consisting of age, CgA, previous treatment lines, tumour type and PS." (PMID 38477040, 2025). "The immunohistochemistry profile was variable according to the primary tumor, CgA, Syn, and keratins were generally positive, while Tg, Ct, and TTF1 were negative." (PMID 40542625, 2025). "The consistent performance of FTIR ratios across tumor grades contrasts sharply with CgA, whose accuracy declines in grade I NETs (sensitivity ~ 60%) and is confounded by proton pump inhibitor use43." (PMID 40624075, 2025). "Immunohistochemical analysis of the tumor section demonstrated strongly positive staining for chromogranin A (CgA), synaptophysin, and a Ki-67 proliferation index ranging from 3% to 20%, leading to the final diagnosis of a SBNET." (PMID 40324239, 2025). "Immunohistochemical staining indicated that the tumor cells expressed Syn, CgA, and CD56, along with a high proliferation index of Ki67." (PMID 40666092, 2025). "Immunohistochemical staining for chromogranin A (CgA) and synaptophysin was performed in all tumor tissue samples, and both markers were positive in all cases." (PMID 41427045, 2025). "CRP, albumin and most composite inflammation scores, but not dNLR, remained as independent prognostic factors for OS after adjusting for age, CgA, PS, Ki‐67, tumour site and number of previous treatments." (PMID 38477040, 2025). "Chromogranin A (CgA) has been used as a valuable tumor marker in NETs, and elevated levels of both CgA and 5-hydroxyindoleacetic acid (5-HIAA) have previously been associated with poor prognosis in these patients." (PMID 40943444, 2025). "While tumor tissue markers of neuroendocrine differentiation, such as CgA and synaptophysin, are available in clinical practice, they require invasive biopsy and immunohistopathological evaluation." (PMID 40038821, 2025). "CgA is a widely used biomarker for NETs, as its levels can correlate with tumor burden, differentiation, and progression." (PMID 40648806, 2025). "Focal positivity for chromogranin A (CgA) and synaptophysin (Syn) was observed in the tumor cells of GCA." (PMID 38500658, 2024). "CgA has been identified as a potential broad-spectrum biomarker for NENs as it correlates with tumor burden, progression, and metastasis." (PMID 38928704, 2024). "Monitoring CgA levels over time can provide insight into treatment efficacy and signal tumor response or progression." (PMID 38928704, 2024). "The same authors highlighted encouraging effects of pasireotide on PFS and disease control, as well as on reduction of tumor markers (CgA, NSE, IGF-1)." (PMID 37581846, 2024). "Age, primary tumor resection, p-CgA and proliferation both expressed by Ki-67 index and WHO grade (in pairwise comparison only G1 vs. NEC was significant) were identified as prognostic factors." (PMID 38201631, 2024). "Combining changes in tumor size (∆size NELM) with CgA or ADCmin showed slight improvements in sensitivities compared to size-based evaluation alone." (PMID 38613843, 2024). "Increased levels of CgA have been shown to be correlated with tumor load, the existence of metastases, and the effectiveness of treatment." (PMID 39314560, 2024). "CgA levels have been classically associated with poor prognosis in GEP-NETs, mostly as they are related to tumor bulk." (PMID 39117670, 2024). "As typical cases presented above, transformed tumor tissues were positive for common NE markers such as Syn and CgA." (PMID 38233864, 2024). "The 2012 WHO Working Group included NENs under the category “carcinomas with NE features” (exhibiting morphological features similar to those of NE tumour of GI tract and lung and expressing NE markers, i.e., chromogranin (CgA) and synaptophysin (Syn)." (PMID 38980337, 2024). "The immunohistochemical results showed that the tumor cells were diffuse and positive for chromogranin A (CgA), synaptophysin (Syn), and INSM1." (PMID 39518315, 2024).
tumor (continued). "We found two proteins, CaCC-1 and CgA, as discriminating factors of both healthy non-tumor and deep tumor tissues with respect to the tumor surface." (PMID 39195201, 2024). "We categorized the possible mechanisms of energy hypermetabolism in PPGL into five categories: catecholamines, BAT activation, inflammation, CgA, and its derivatives, and their impact on tumor behavior." (PMID 38669419, 2024). "Cultures of the primary tumor were positive for many neuroendocrine markers over several passages, including CgA, NSE, somatostatin, SSTRs, and gastrin, among others." (PMID 39649120, 2024). "The European Neuroendocrine Tumour Society recognises CgA as a reliable blood tumour marker for patients with NETs." (PMID 39036213, 2024). "For instance, CgA levels vary according to tumor function and location, appearing to be higher in well-differentiated than in poorly differentiated, functional than in non-functional, and metastatic than in locoregional disease." (PMID 37685358, 2023). "In terms of immunophenotype, the tumor tissues express chromogranin A (CgA), synaptophysin (Syn), and CD56." (PMID 37724114, 2023). "The tumor cells were strongly positive for CgA and synaptophysin, with a Ki67 labeling index of 3.0%." (PMID 37867522, 2023). "The percentage of serum CgA-related tumor marker responders (CR + PR) steadily increased in the 12 months following the first therapeutic dose reaching 68% (19/28)." (PMID 36472300, 2023). "It has been shown that CgA can affect several elements in the tumor microenvironment, including endothelial cells and fibroblasts." (PMID 37623030, 2023). "Elevations in CgA levels have been shown to correlate with tumor burden, presence of metastases, and response to treatment." (PMID 37190177, 2023). "Immunohistochemistry of tumor cells has a different expression of neuroendocrine markers, including CgA, Syn, and NSE." (PMID 37194067, 2023). "The tumor marker Chromogranin A (CgA) is commonly used in clinical practice for monitoring patients with NEN." (PMID 37318593, 2023). "After H and E staining and immunohistochemical staining, some tumor cells showed typical positive synaptophysin (Syn) and Chromogranin (CgA) staining." (PMID 36836889, 2023). "The immunobiological study of the tumour markers typically demonstrates positivity of neuron-specific enolase (74.1–90%), CgA (66.7–95%), and synaptophysin (48.9–91.7%) and CD56 and cytokeratin." (PMID 37386646, 2023). "Tumor cells express both epithelial and neuroendocrine markers including CgA, synaptophysin, NSE, CD57, CD56, PGP9.5 and ‘dot-like’ cytokeratins." (PMID 38137784, 2023). "As seen in our cohort, laboratory testing of CgA-levels during oncological follow-up is an excellent tool to early diagnose tumor recurrence, as elevated levels correlate with tumor burden." (PMID 37077861, 2023). "The presence of CTCs in the blood correlates with increased tumor burden, grade, and serum CgA levels." (PMID 37685358, 2023). "For serum tumor markers, ratios of completed diagnostics varied among the patients, with CgA being the most frequently (66%) and CEA (24%) the least frequently assessed marker." (PMID 37686593, 2023). "Tumor recurrence was detected during oncological follow-up, on the one hand due to elevated CgA-levels, on the other hand, via imaging (PET-CT, CT-scan)." (PMID 37077861, 2023). "Here, we focused on the serum tumor markers CgA and NSE, as well as 5-hydroxyindoleacetic acid, as a central metabolite of serotonin." (PMID 37686593, 2023). "The best overall serum CgA-related tumor marker response rates (CR + PR) were observed to be slightly higher (80%) than total metanephrines (70%)." (PMID 36472300, 2023). "The degree of diagnostic efforts performed at the primary diagnosis was rated based on the performance rates of (I) immunohistochemical and (II) endoscopic analyses, (III) PET-based imaging and the investigation of (IV) serum tumor markers (CgA and NSE)." (PMID 37686593, 2023).
tumor (continued). "Mono-analyte biomarkers are specific molecules (i.e., CgA, circulating tumor cells, and serotonin) detectable in the blood or other body fluids used to diagnose tumors, detect the presence of disease, and monitor tumor progression." (PMID 37685358, 2023). "Syn and CgA IHC images showed that the cytoplasm of some tumor cells was colored to varying degrees, showing scattered or large patchy light brown to dark brown staining." (PMID 38125789, 2023). "NETs of the breast were defined as tumors of epithelial origin with neuroendocrine marker (CgA and/or Syn) expression in more than 50% of tumor cells." (PMID 35692784, 2022). "The results obtained so far suggest that integrins (particularly the integrin αvβ6) and neuropilin-1 are important receptors that mediate relevant pathophysiological functions of CgA and its fragments in angiogenesis, wound healing, and tumor growth." (PMID 36559048, 2022). "The immunohistochemical results showed that 21/23 and 13/13 of the tumor cells showed positive reactions of CgA and Syn, suggesting that some tumor cells have potential endocrine functions." (PMID 35558392, 2022). "Several studies report the predictive value of tumor biochemical response assessed by changes in CgA levels for PFS and OS in panNEN patients treated with chemotherapy." (PMID 35267558, 2022). "Several biomarkers, such as tumor grade, Ki-67 index, and CgA, aid in the clinical management of PanNET patients; however, there is a need to identify novel, reliable, and accessible biomarkers." (PMID 35163032, 2022). "Rather, TR was related to hepatic tumour burden and elevated plasma CgA and 5-HIAA concentrations, i.e., to the severity of CS." (PMID 35536452, 2022). "Risk factors for a hormonal crisis include CS, elevated 5-hydroxyindoleacetic acid (5-HIAA) and CgA levels, metastatic disease, high tumor burden, higher age and histamine release due to medication as β2 agonist bronchodilators." (PMID 36497273, 2022). "Elevated bodily fluid concentrations of different granins (most notably CgA) among patients with hormonally active neoplasms have been some of the most important observations established in that research and with far-reaching clinical implications." (PMID 36233409, 2022). "Given that no CgA was produced by cancer cells in the models studied, it is very likely that these fragments were generated by cleavage of bloodborne CgA in tumor lesions." (PMID 36559048, 2022). "In 47 patients, the complete biochemical course of the tumour marker CgA was evaluated before, during and after STZ CTx." (PMID 34480724, 2022). "In GEP-NENs, both Syn and CgA are highly expressed in well-differentiated neoplasms, whereas poorly differentiated carcinomas often maintain synaptophysin positivity while losing CgA expression and acquiring NSE expression." (PMID 35794609, 2022). "After adjusting for tumor size, grade, clinical nodal status, and academic status of the facility, CgA levels (CgA high versus CgA low) independently predicted overall survival (hazard ratio: 7.90, 95% CI: 2.34–26.69, p = 0.001)." (PMID 36615051, 2022). "Circulating CgA is correlated with tumor progression, metastasis, and response to treatment in PNENs." (PMID 36615051, 2022). "The main findings of our study were that mean mRNA levels of many EMT markers were consistently higher in tumour tissue relative to those in non-tumour tissue in all three grades, as well as the existing diagnostic markers CD56, CgA and Ki-67." (PMID 36362433, 2022). "Immunohistochemical staining of the tumors showed that the positive rates of chromogranin A (CgA) and synaptophysin (Syn) were 21/23 and 13/13, respectively, which showed varying numbers of brown granules in the cytoplasm of tumor cells." (PMID 35558392, 2022). "The western blot detected a significantly decreased CGA expression level in PDAC cells compared to HPDE6-C7 cells, suggesting the tumor suppressor role of CGA in PDAC." (PMID 35521536, 2022).